PIK3R1 (phosphoinositide-3-kinase regulatory subunit 1)
Diseases named in the same sentence as PIK3R1 in open-access papers (continued):
Sharing a sentence is not in itself a finding about the gene and the disease.
glioblastoma (continued). "On the other side PIK3R1, encoding for the regulatory subunit p85 of PI3K, shows mutations especially in ovarian, colon, endometrial, prostate cancer, glioblastoma and also in malignant melanoma." (PMID 29100280, 2017). "Studies have also suggested that PIK3R1 expression negatively influences glioblastoma tumour growth and patient survival." (PMID 26501081, 2015). "PIK3R1 has been suggested as a potential therapeutic target in several cancers including glioblastoma multiforme and NSCLC." (PMID 24403257, 2013). "shRNA-mediated knockdown of either the PIK3CA or PIK3R1 gene resulted in reduced proliferation, migration, and invasion in glioblastoma cell lines, and in the case of the PIK3R1 gene these effects are independent of the Akt pathway." (PMID 22064833, 2011). "Finally, we identified novel small molecules that effectively targeted cells carrying mutant BRAF and PIK3R1, implying their potential for personalized glioblastoma therapy." (PMID 33313992, 2021). "Surely, decrease of PIK3R1 suppressed proliferation and invasion in glioblastoma multiform cells." (PMID 32817745, 2020). "PIK3R1 is very frequently mutated in other cancer histotypes, with the notable exception of HGS-EOC, in particular in uterine carcinomas and carcinosarcomas, glioblastoma, breast and colorectal cancer." (PMID 32075097, 2020). "Therefore, the interactions between PIK3R1 mutation, TERT promoter mutation and PIK3CA mutation in adult glioblastoma clinical characteristics remain to be determined." (PMID 31036078, 2019). "PIK3R1 mutations have been shown to induce a gain of PI3K enzymatic function and enhance PI3K signaling, which implies that PIK3R1 mutant glioblastomas may well have the similar impact as the PIK3CA mutant counterpart." (PMID 31036078, 2019). "Further, NFBTA down-regulation of phosphoinositide-3-kinase regulatory subunit 1 (PIK3R1) genes augments its anti-glioblastoma efficacy, since knockout or silencing of PIK3R1 genes evokes the responses of decreased proliferation, migration, and invasion in 081,110, and 081,024 GBM cell lines." (PMID 31261921, 2019). "Studies concerning glioblastomas have also suggested that these tumors might be negatively influenced by PIK3R1 expression at the level of cell lines and in terms of patient survival." (PMID 24229379, 2013). "Here, we found that several of the most frequently mutated genes in glioblastoma including: EGFR, PTEN, NF1, PIK3R1, RB1, PDGFRA and QKI possessed high 5 hmC levels across intronic regions and further loss of 5 hmC in tumours may reflect a loss of genome integrity." (PMID 27886174, 2016). "Notably, while both PIK3CA and PIK3R1 knockdown significantly reduces FAK activity in D54 glioblastoma cells, only reduction in PIK3R1 expression results in statistically significantly slowed cell migration, supporting the only partial role played by FAK signaling in GBM cell motility." (PMID 22064833, 2011). "Similarly, PIK3R1 knockdown reduced MMP2 and uPA levels in neurospheres, and reduced MMP2 and MMP9 levels in D54 cells, and reduction of the levels of these proteins has been shown to cause reduced migratory and invasive capacity in glioblastoma cells." (PMID 22064833, 2011). "This list includes cell surface expressed markers such as GPRC5, signaling molecules such PIK3R1 and the histone deacetylase, HDAC9, for which small molecule inhibitors are currently under investigation in glioblastoma clinical trials." (PMID 20423517, 2010). "Unlike these, the mutations in SEGA-like glioblastoma occurred in the context of other genetic aberrations present in high-grade neoplasms, including in the CDKN2A/B, PIK3R1, PIK3CA and EGFR genes." (PMID 31258848, 2019).
glioblastoma (continued). "Using netboxr, we identify the PIK3R1 (Module M1) and RB1 (Module M2) modules, each with connected genes that are significantly altered as a set in the glioblastoma (GBM) cancer genomics data from the Cancer Genome Atlas (TCGA)." (PMID 33137091, 2020). "Interestingly, tumors lacking PIK3CA mutations often harbored mutations in PIK3R1, with significant occurrences in UCEC (31%) and glioblastoma multiforme (GBM) (11%)." (PMID 38920700, 2024).
SHORT syndrome (40 papers, 2014 to 2026). A rare disorder characterized by multiple congenital anomalies, including short stature, hyperextensibility of joints, ocular depression, Rieger anomaly and teething delay in which the cause of the disease is a mutation in PIK3R1 gene. "In SHORT syndrome, mutations in PIK3R1 impair the inhibitory function of p85α, disrupting the interaction between this subunit and the IRS molecule and leading to the impairment of the PI3K‐Akt signaling pathway." (PMID 40860302, 2025). "SHORT syndrome was diagnosed in patient 80 harboring heterozygous c.1945C > T (p.R649W) variant to the PIK3R1 gene." (PMID 39504571, 2025). "We now set out to investigate the source of the unexplained “energy leak” of the Pik3r1 Y657* mouse model of SHORT syndrome, assessing BAT activity, heat loss through the tail vein, and thermal insulation." (PMID 40152560, 2025). "Specifically, in SHORT syndrome, which features severe IR and is caused by heterozygous PIK3R1 mutations, serum triglyceride concentrations and liver triglyceride contents are surprisingly normal or low." (PMID 40152560, 2025). "SHORT syndrome is a rare inherited disease with 34 identified pathogenic or likely pathogenic PIK3R1 mutations." (PMID 40860302, 2025). "According to the ClinVar database of the US National Institutes of Health, 34 mutations in the PIK3R1 gene have been identified as pathogenic and likely pathogenic for SHORT syndrome." (PMID 40860302, 2025). "Human SHORT syndrome is caused by dominant negative human PIK3R1 mutations that impair insulin-stimulated phosphoinositide 3-kinase (PI3K) activity." (PMID 40152560, 2025). "SHORT syndrome is caused by mutations in the phosphoinositide‐3‐kinase regulatory subunit 1 (PIK3R1) gene, which is located on the long arm of chromosome 5." (PMID 40860302, 2025). "In contrast, PIK3R1 mutations associated with SHORT syndrome often result in de novo truncations of p85α, leading to reduced activation of the PI3K-AKT-mTOR pathway, which in turn causes developmental delays, lipodystrophy, and distinct facial features." (PMID 40568112, 2025). "The variant is not found in the gnomAD genome and it involves a loss‐of‐function mutation in the PIK3R1 gene, which is a known mechanism for SHORT syndrome." (PMID 40860302, 2025). "This novel pathological homozygous mutation in the PIK3R1 gene highlights the association of agammaglobulinemia with SHORT syndrome." (PMID 39044864, 2024). "Heterozygous loss-of-function mutations in PIK3R1 can also result in SHORT syndrome, which is characterized by Short stature, Hyperextensibility of joints and/or hernias, Ocular depression, Rieger anomaly and delays of Tooth eruptions." (PMID 39679264, 2024). "Heterozygous PIK3R1 mutations are the major cause of SHORT syndrome (each letter in the term SHORT represents a feature: (S) Short stature, (H) Hyperextensibility of joints and/or Hernia, (O) Ocular depression, (R) Rieger anomaly, (T) Teething delay)." (PMID 39044864, 2024). "PIK3R1 mutations were identified in SHORT syndrome in 2013, nearly all in the C-terminal SH2 domain, which together with the N-terminal SH2 domain enables PI3K recruitment to activated RTKs." (PMID 38077044, 2024). "Although heterozygous loss-of-function PIK3R1 variants usually result in either APDS2 or SHORT syndrome, a few patients with exon 11 skipping PIKR1 variants, have been described with overlapping features." (PMID 39679264, 2024). "Pathogenic variants for SHORT syndrome are enriched within the cSH2 domain of PIK3R1 and observed in the iSH2 domain." (PMID 38541623, 2024). "This case reveals the association of the PIK3R1 gene mutation with agammaglobulinemia and SHORT syndrome." (PMID 39044864, 2024). "In contrast to APDS2, the PIK3R1 variants associated with SHORT syndrome are typically located in the inter-SH2 or C-terminal SH2 domains of the p85α." (PMID 39679264, 2024).
SHORT syndrome (continued). "Phosphoinositide-3-kinase regulatory subunit 1 (PIK3R1) gene mutations are associated with SHORT syndrome, a rare multisystem disease." (PMID 39044864, 2024). "Hereditary insulin resistance syndromes include genetic syndromes caused by INSR mutations, SHORT syndromes caused by PIK3R1 abnormalities, and conditions caused by AKT2, TBC1D4, or PRKCE abnormalities." (PMID 36626508, 2022). "The patient had an atypical germline variant of PIK3R1 [NM_181523.3:c.1457C>T, p.(Ala486Val)] in the iSH2 domain, which is a rare site of germline mutations, in patients with Short syndrome." (PMID 34440292, 2021). "Mutations in PIK3R1 cause agammaglobulinemia 7, immunodeficiency 36, and SHORT syndrome, which is characterized by short stature, hyperextensibility of joints, ocular depression, Rieger anomaly, and teething delay." (PMID 34450027, 2021). "Clinical exome sequencing showed a heterozygous pathogenic variant, NM_181523.3:c.1945C>T (p.Arg649Trp) in exon 15 of the phosphoinositide-3-kinase regulatory subunit 1 (PIK3R1) known as the causative gene for SHORT syndrome." (PMID 34249805, 2021). "In this study, we report two Chinese girls presenting with complicated clinical manifestations who were finally diagnosed with SHORT syndrome due to a mutation in the PIK3R1 gene." (PMID 32602265, 2020). "We identified two de novo heterozygous mutations in PIK3R1 as the cause of SHORT syndrome in two Chinese girls." (PMID 32602265, 2020). "SHORT syndrome is caused by mutations in PIK3R1; encoding components of the insulin signalling enzyme phosphoinositide 3-kinase (PI3K)." (PMID 32439336, 2020). "Before the discovery of PIK3R1 mutations in SHORT syndrome, Pik3r1 had been intensively studied in mice." (PMID 32439336, 2020). "To date, 10 different mutations in the PIK3R1 gene have been reported as the underlying cause of SHORT syndrome." (PMID 32602265, 2020). "SHORT syndrome is associated with multiple mutations in the PIK3R1 gene (5q13.1), which encodes phosphatidylinositol 3‐kinase regulatory subunit alpha." (PMID 32602265, 2020). "PIK3R1 mutation is associated with two different conditions, that are SHORT syndrome and a rare primary immunodeficiency disorder named Activated PI3K-delta Syndrome 2 (APDS2, MIM615513)." (PMID 33129256, 2020). "Next, we tested a panel of germ line PIK3R1 mutations linked to the genetically inherited SHORT syndrome." (PMID 28143957, 2017). "This demonstrates that the effect of this SHORT syndrome PIK3R1 mutation on insulin signaling is cell type specific." (PMID 27766312, 2016). "An autosomal dominant mutation in the PIK3R1 gene in patients with SHORT syndrome was previously identified." (PMID 27142333, 2016). "In 2013, mutations in PIK3R1 were also demonstrated to cause SHORT syndrome, denoting short stature, joint hyperextensibility, ocular depression, Rieger anomaly (a developmental defect in the iris), and teething delay." (PMID 27766312, 2016). "We report 5 patients with SHORT syndrome and C-terminal mutations in PIK3R1, encoding the p85α/p55α/p50α subunits of PI3K, which act between INSR and AKT in insulin signaling." (PMID 27766312, 2016). "The clinical syndromes and PIK3R1 mutations we describe are consistent with previous reports of SHORT syndrome." (PMID 27766312, 2016). "While this study was underway, 3 groups independently reported C-terminal PIK3R1 mutations, including both p.Tyr657X and p.Arg649Trp, to be the cause of SHORT syndrome." (PMID 27766312, 2016). "Recently, four groups have independently reported the finding of mutations in PIK3R1 as the primary cause of SHORT syndrome." (PMID 24886349, 2014). "In this study, we describe the use of whole-exome sequencing technology to identify a novel PIK3R1 mutation, as well as a point mutation already reported in this gene, in two patients with SHORT syndrome." (PMID 24886349, 2014).
SHORT syndrome (continued). "In summary, by using whole-exome capture and next-generation sequencing, we report PIK3R1 as the gene implicated in SHORT syndrome in two patients, further supporting the recently published works about this syndrome." (PMID 24886349, 2014). "We show evidence of the causative role of mutations in PIK3R1 in SHORT syndrome, adding to the recently published papers that show mutations in this gene in other patients with this progeroid syndrome." (PMID 24886349, 2014). "Consistent with a role in mediating growth, PIK3R1 mutations in humans result in SHORT syndrome, a developmental disorder characterised by severe defects in fetal growth, although no parent-of-origin effects have been reported in the presentation of this disease." (PMID 40568952, 2025). "SHORT syndrome is attributed to heterozygous mutations of PIK3R1 located on chromosome 5." (PMID 39044864, 2024). "Mice with SHORT syndrome mutations knocked in were generated after human findings, and faithfully reproduce the human phenotype, confirming that expression of a signalling-impaired PIK3R1 has different consequences to Pik3r1 knockout." (PMID 38077044, 2024). "Multiple mutations in human PIK3R1 have been associated with SHORT syndrome." (PMID 37628845, 2023). "This clinical observation suggests that SHORT syndrome, due to variants in the iSH2 domain of PIK3R1, might be a leukemia predisposing syndrome." (PMID 34440292, 2021). "SHORT syndrome is a rare inherited multisystem disease that includes characteristic facial features, growth retardation, and metabolic anomalies and is related to heterozygous mutations in the PIK3R1 gene." (PMID 32602265, 2020). "A critical insight from the study of SHORT syndrome was that the insulin signalling role of PIK3R1 could be severely attenuated by neomorphic mutations disrupting the C-terminal SH2 domain." (PMID 32439336, 2020). "SHORT syndrome is caused by mutations in the PIK3R1 gene (5q13.1), encoding phosphatidylinositol 3‐kinase regulatory subunit p85α, which plays an important role in chemical signal transduction within cells, including cell growth and proliferation, protein synthesis, and the maturation of adipocytes." (PMID 32602265, 2020). "In 2013, heterozygous mutations in PIK3R1 were established as the major cause of SHORT syndrome, a rare disease characterized by short stature, delayed dentition, characteristic facial features, ocular depression, lipodystrophy and hyperextensibility of joints (OMIM 269880)." (PMID 31939486, 2019). "In support of this hypothesis, autosomal dominant mutations in the last exons of PIK3R1 cause SHORT syndrome (short stature, hyperextensibility of joints and/or hernias, ocular depression, Rieger anomaly, and delays of tooth eruption)." (PMID 30319630, 2018). "PIK3R5, is a regulatory subunit of the class I phosphatidylinositol 3-kinase (PI3K) gamma complex and it has been shown that mutations in another PI3K regulatory gene subunit, PIK3R1, are responsible for human short syndrome, which is characterized by a variety of symptoms including short stature." (PMID 28454565, 2017). "The heterozygous male mice (Pik3r1+/R649W) show several phenotypes that are similar to SHORT syndrome phenotypes." (PMID 37628845, 2023). "Our data along with previous findings regarding the effect of inhibitory mutation of PIK3R1 on SHORT syndrome-associated inguinal hernia indicate that the PI3K pathway, especially the essential protein, PIK3R1 is necessary for inguinal hernia development." (PMID 31910207, 2020). "After searching the literature, we also found that there were correlations between genotype in PIK3R1 and the phenotype of SHORT syndrome to a certain extent." (PMID 32602265, 2020). "After searching the literature, we found that there were correlations between genotype in PIK3R1 and the phenotype of SHORT syndrome to a certain extent." (PMID 32602265, 2020).
SHORT syndrome (continued). "This is indeed the case, as the new version of OMIM links SHORT syndrome to gene PIK3R1, which has a verified in-vitro interaction with IRS1, a gene associated to noninsulin-dependent diabetes." (PMID 26631976, 2015). "Whole exome sequencing revealed a heterozygous pathogenic variant in exon 15 of the regulatory subunit of phosphoinositide 3-kinase 1 (PIK3R1) gene, leading to a genetic diagnosis of SHORT syndrome (short stature, joint hyperextensibility, ocular depression, rieger anomaly, and teething delay)." (PMID 41948357, 2026). "Our case showed a homozygous mutation in the PIK3R1 gene and revealed some features of SHORT syndrome such as hyperextensibility, vision abnormalities, lack of fat tissue, triangular face, extroverted ears, ocular depression, developmental and teething delay." (PMID 39044864, 2024). "In contrast to SHORT syndrome, mutations in the inter SH2 domain of PIK3R1, mostly leading to skipping of exon 11, were shown in 2014 to activate PI3K in vitro and to cause immunodeficiency (APDS2) similar to that caused by activating mutations in p110δ (APDS1)." (PMID 38077044, 2024). "Based on these findings, we hypothesised that the hypolipidemia seen in Pik3r1WT/Y657∗ mice would be accounted for by reduced hepatic de novo lipogenesis, as in SHORT syndrome due to PIK3R1 Y657∗." (PMID 32439336, 2020). "Molecular studies have shown that PIK3R1 mutations associated with SHORT syndrome result in defects, and not in the activation of PI3K signalling." (PMID 32075097, 2020). "The mechanism of how mutations in PIK3R1 result in the complex phenotype of SHORT syndrome is not completely understood." (PMID 31939486, 2019). "The first patient described herein presents a novel frameshift mutation in PIK3R1 that has no similarity with any mutation reported before in the context of SHORT syndrome." (PMID 24886349, 2014). "Pathogenic mutations in PIK3R1 affect different protein domains and are associated with various disorders, including activated PI3K-δ syndrome 2 (APDS2), characterized by hypogammaglobulinemia and immune dysregulation, and SHORT syndrome, marked by short stature and endocrine abnormalities." (PMID 40568112, 2025). "Besides often being insulin resistant, SHORT syndrome patients with mutations in PIK3R1 do not exhibit fatty liver." (PMID 37628845, 2023). "Biochemical studies demonstrate that differences between SHORT syndrome and APDS2 are attributable to different profiles of activation or repression of PIK3CA and PIK3CD by mutant PIK3R1 products." (PMID 34040190, 2021). "All people with SHORT-APDS2 overlap syndromes have well established activating PIK3R1 mutations in the inter-SH2 domain implicated in APDS2, but none have characteristic SHORT syndrome mutations, which are usually in the C-terminal SH2 domain." (PMID 38077044, 2024). "Pik3r1 dysfunction in mice phenocopies the IR and reduced adiposity without lipotoxicity of human SHORT syndrome." (PMID 32439336, 2020).